GPR150 (G protein-coupled receptor 150)
Description:
Orphan receptor.
Synonyms: PGR11
Tractability: Small molecule: it belongs to a druggable protein family. Antibody: its Gene Ontology location is reachable by antibodies, with high confidence; UniProt places it where antibodies can reach, with medium confidence; UniProt predicts a signal peptide or a membrane-spanning region.
Target class: Family A G protein-coupled receptor; Membrane receptor
Gene: Protein-coding gene on chromosome 5 (95,620,087 to 95,622,142, forward strand). Ensembl gene ENSG00000178015.
Subcellular location: Cell membrane
Pathways (Reactome):
Signal Transduction: G alpha (s) signalling events
Gene Ontology:
Molecular function: G protein-coupled receptor activity
Biological process: cellular response to hormone stimulus; G protein-coupled receptor signaling pathway
Cellular component: plasma membrane; membrane
Genetic constraint (gnomAD): Loss-of-function variants: 24 observed, 12.6 expected, observed/expected ratio (o/e) 1.9, 90% interval 1.29 to 1.97. The synonymous counts are far from expectation, so gnomAD's model fits this gene poorly and the ratio says little. Missense variants: 714 observed, 459.58 expected, observed/expected ratio (o/e) 1.55, 90% interval 1.46 to 1.65. Synonymous variants: 347 observed, 225.24 expected, observed/expected ratio (o/e) 1.54, 90% interval 1.41 to 1.68.
Homologues: Orthologues: chimpanzee GPR150 (99% identical), macaque GPR150 (96% identical), pig GPR150 (76% identical), rabbit GPR150 (75% identical), Drosophila melanogaster CrzR (18% identical), Caenorhabditis elegans daf-38 (15% identical). Paralogues in human: AVPR1B (22% identical), AVPR1A (21% identical), OXTR (21% identical), AVPR2 (19% identical), CCKBR (16% identical), GNRHR (16% identical), NPFFR1 (15% identical), HCRTR1 (15% identical), CCKAR (15% identical), FFAR4 (15% identical), GALR3 (15% identical), HCRTR2 (15% identical), and 4 more.
Diseases named in the same sentence as GPR150 in open-access papers:
GPR150 is named in the same sentence as 2 diseases in open-access papers, as found by Europe PMC text mining. Sharing a sentence is not in itself a finding about the gene and the disease. The quoted sentences say what the papers report.
ovarian carcinoma (2 papers, 2024 to 2025). A malignant neoplasm originating from the surface ovarian epithelium. "Aberrant methylation of GPR150 may be a candidate tumor marker for ovarian cancer." (PMID 40689396, 2025).
tumor (3 papers, 2006 to 2025). "Patients with hypomethylation of PAX9, STK33, GPR150, INSM1, and EPHX3 showed a shorter survival time and a higher tumor‐related mortality." (PMID 31131446, 2019).